EGFR (epidermal growth factor receptor)
Diseases named in the same sentence as EGFR in open-access papers (continued):
Sharing a sentence is not in itself a finding about the gene and the disease.
tumor (continued). "Based on its ability to inhibit EGFR signaling by binding to dimerization domain II, block the PD-1/PD-L1 interaction and mediate specific cellular recognition to EGFR/PD-L1 double-positive tumor cells, HCP-LCE was chosen as a starting molecule to introduce a NK cell engaging module." (PMID 37081888, 2023). "The absence of tumor response to standard EGFR TKIs and suboptimal efficacy of chemotherapy highlight the cruciality of identifying targeted therapy with activity against EGFR exon20ins mutations in NSCLC." (PMID 36979929, 2023). "However, ligands binding to wild-type EGFR can inhibit EGFRvIII and tumor growth." (PMID 38264122, 2023). "Therefore, inhibition of the EGFR pathway may somewhat reduce PD-L1 expression caused by IFN-γ stimulation, thus enhancing the tumor-killing activity of infiltrated immune cells." (PMID 37759950, 2023). "In that case, there is an option of a second-line therapy: the decision to choose the appropriate second-line treatment largely depends on whether the EGFR T790M mutation is present or absent, which can be detected in either plasma or tumor tissue." (PMID 38201251, 2023). "Of relevance, PKCδ represents one of the immune rheostats responsible for the establishment of non-inflamed phenotype in EGFR-mutated lung cancer, also by increasing the expression of PD-1 ligand PD-L1 on tumor cells, leading to immune exclusion and cancer escape from T cell surveillance." (PMID 37626933, 2023). "Tumor genomic profiling was completed prospectively at the discretion of treating clinicians, and we included all consecutive patients with genomic profiling, including patients with EGFR driver alterations who are less likely to derive benefit from the PACIFIC regimen." (PMID 36602799, 2023). "Furthermore, the CHP score was related to resistance against multiple anti-tumor drugs,e.g., mitosis and DNA replication inhibitors, whereas epidermal growth factor receptor (EGFR) pathway inhibitors were identified as potentially therapeutically beneficial for tumors with a high CHP score." (PMID 36761982, 2023). "For the meta-regression analysis, we also selected the same 9 variables (year, region, phase, immunotherapy inhibitor, anti-angiogenic drug, tumor histology, study design, EGFR mutation and whether or not to combine chemotherapy)." (PMID 37614237, 2023). "In addition, we analyzed EGFR and Sorcin phosphorylation: the average increase of phosphorylation in tumors (phosphorylation in each tumor/phosphorylation in normal surrounding tissue ratio) was obtained for each type of tumor for EGFR and SRI." (PMID 37442828, 2023). "Studies have shown that the EGFR/ERK signaling pathway might be a new anti-tumor pathway." (PMID 37151068, 2023). "Previously, we reported that NANOG was a crucial transcription factor driving the multi-refractory phenotypes of tumor cells, such as stem-like, metastatic and anti-apoptotic properties and resistance to multi-modal therapies via autophagy-mediated hyperactivation of the EGFR-AKT pathway." (PMID 37165076, 2023). "However, the clinical efficacy is limited in patients carrying EGFR alterations, indicating that EGFR signaling may involve tumor immune response." (PMID 37601668, 2023). "Indeed, specific EGFR mutations confer sensitivity to selective EGFR-TKI inhibitors, thus allowing a targeted therapy, based on the molecular profile of the tumour, with the potential of improving the patient’s overall and progression-free survival, compared to standard chemotherapy." (PMID 38116291, 2023). "Several semiquantitative metabolic parameters, such as SUVmax, metabolic tumor volume (MTV), and total lesion glycolysis (TLG), which reflect 18F-FDG metabolic activity as measured by PET/CT, have been shown to be effective in predicting the status of EGFR mutation in patients with NSCLC." (PMID 36983578, 2023).
tumor (continued). "Similarly, CTSK can promote CRC progression by promoting M2 polarization of TAM through a TLR4-mTOR-dependent pathway, while M2 macrophages can secrete chemokines such as IL7 and EGFR to activate the NFκB pathway to further promote tumor tissue invasion and metastasis." (PMID 37930479, 2023). "Notably, NF-κB can facilitate the epithelial-mesenchymal transition (EMT) of tumor cells, which may constitute one of the potential mechanisms by which TAMs mediate resistance to EGFR-TKIs." (PMID 37649478, 2023). "Thus, attention should be payed to implementation of a sensitive indel calling in bioinformatic pipelines to avoid missing of clinically relevant alterations such as for example activating indels in the exon 19 of the EGFR gene or truncating indels in tumor suppressor genes." (PMID 37864096, 2023). "Therefore, AuNP-NmAb could be used as it shows enhanced anti-tumor activity in low- and medium-EGFR-expressing cancer cells compared to NmAb only." (PMID 37623652, 2023). "Additionally, most oncogene-driven NSCLC tumours initially responding to targeted therapies such as epidermal growth factor receptor (EGFR)-tyrosine kinase inhibitors (TKI) and anaplastic lymphoma kinase (ALK) inhibitors eventually progress over time as they acquire drug resistance." (PMID 37386452, 2023). "In this regard, results from recent studies have suggested that the hyperactivation of EGFR signaling could be one of major pathway that drives the adaptation of tumor cells to cisplatin, thereby contributing to the generation of cancer cells with better survival advantages." (PMID 37165076, 2023). "Moreover, a recent study demonstrated that treatment with EGFR-TKIs may change the tumor microenvironment by increasing PD-L1 expression and TMB, while modifying CD8+/FOXP3 TILs and CD73 expression." (PMID 37240224, 2023). "Overexpression of cortactin could contribute to the emergence of invasive tumor phenotypes in a variety of ways, including enhanced actin polymerization, down-regulated epidermal growth factor receptor, and molecule interactions between cyclin D1 and CD44 proteins." (PMID 38077360, 2023). "Likewise, as demonstrated here, not only drugs targeting the VEGF axis can overcome tumor endothelial cell anergy, also drugs targeting epithelial growth factor receptor (EGFR, erlotinib) and platelet derived growth factor receptor (PDGFR, crenolanib) can normalize ICAM-1 expression." (PMID 36459240, 2023). "Leveraging these distinct spatial distributions of EGFR expression may yield contrast-enhanced visualization of tumor in HNSCCs relative to using fluorescence intensity alone, which by itself, does not incorporate spatial relationships or patterns in local fluorescence." (PMID 36875185, 2023). "Deletion of T790M may be misinterpreted as resensitization of tumor cells to first-line EGFR TKIs." (PMID 37041601, 2023). "In this study, we created and characterized diagnostic and therapeutic stem cells (SC), expressing EGFR-targeted nanobody (EV) fused to the extracellular domain of death DR4/5 ligand (DRL) (EVDRL) that simultaneously targets EGFR and DR4/5, in primary and metastatic NSCLC tumor models." (PMID 37311043, 2023). "In addition to the use of cyclic RGD peptides to deliver siRNA, GE11 peptide is also used, which is an anti-EGFR peptide that can actively bind to TNBC cells overexpressing epidermal growth factor receptor (EGFR), which is beneficial for siRNA to better target these tumor cells." (PMID 37691919, 2023).
tumor (continued). "Indeed, exosomal transfer of tumor-derived EGFR to both local and distant recipient cells has been found to promote cancer cell growth, metastases and drug resistance as well as angiogenesis, metastatic niche formation, and suppression of anti-tumor immunity." (PMID 36817764, 2023). "The ongoing randomized PARERE study, investigating rechallenge with panitumumab followed by regorafenib versus the reverse sequence in chemorefractory RAS/BRAF wt patients selected by liquid biopsy, could further clarify the role of anti-EGFR according to primary tumor site." (PMID 36895480, 2023). "Moreover, clinical trials in EGFR mutation-positive tumours for gefitinib and erlotinib showed a higher response rate of 68% compared to 8–9% in mutation-positive tumours lacking EGFR mutation." (PMID 37686122, 2023). "Conjugation of EGFR-specific peptides to the surface of anticancer drug-loaded nanoparticles could be a more effective therapeutic strategy focusing on drug delivery to mesenchymal TNBC tumor masses." (PMID 37048151, 2023). "In addition, TNS4 could inhibit the degradation of EGFR, a molecule related to tumor cell proliferation and apoptosis inhibition, through post-translational modification, and prolonged its function." (PMID 37328854, 2023). "Thus, modulation of the EGFR activity via PAHs and other AhR ligands could be a contributing factor to cancer cell proliferation and tumor promotion." (PMID 37696458, 2023). "Thus, lnc-EGFR could potentially provide valuable insights into the tumor–stroma immune interaction via extracellular vesicles in CRC." (PMID 37760852, 2023). "Therefore, we hypothesized that Curcumin could enhance the anti-tumor effects of Lenvatinib as a tyrosine kinase inhibitor, and that its anti-EGFR potential could help overcome the Lenvatinib resistance in HCC." (PMID 36831279, 2023). "Moreover, the receptor activation has been found to stimulate the tumor cells to invade and migrate to healthy tissues via one of the Gα proteins or transesterification of the epidermal growth factor receptor (EGFR), which is said to influence the GRPR-stimulated DNA synthesis in tumor cells." (PMID 36834867, 2023). "Up to now, the advanced NSCLC patient with p.E746_S752delinsI still benefited from Icotinib treatment for a total of 19 months, with decreasing tumor burden and CEA level, which showed advanced LADC patients harboring EGFR p.E746_S752delinsI mutation could benefit from Icotinib." (PMID 37795433, 2023). "Pairwise comparisons indicated that the mean tumor size for the KRAS mutation-positive group was significantly larger than that of the ALK mutation-positive group (p = 0.01), which was significantly larger than that of the EGFR mutation-positive group (p = 0.001)." (PMID 37508989, 2023). "Although the optimal threshold of tumor volume for texture analysis varies across studies, previous studies have suggested that combining promising parameters, such as PET and CT, may be helpful for identifying the EGFR mutation status." (PMID 37185611, 2023). "Exosomal EGFR levels in the plasma of xenograft mice exhibited the same trend as the growth of xenograft tumors, suggesting that these levels could be used to assess tumor size." (PMID 36834471, 2023). "Except for inhibiting tumor cell viability directly, EGFR-TKIs could also enhance the immune function of T cells by downregulating the expression of PD-L1 and enhancing the production of interferon-γ (an indicator of T-cell function) as revealed in a cell study." (PMID 36949948, 2023). "Thus, it would be interesting to investigate in future work whether the DGKζ/ERK3 axis plays differential roles in migration, invasiveness, and tumor progression of NSCLCs with different statuses of KRAS or EGFR." (PMID 37287450, 2023). "When the tumor progresses to Advanced-Ad stages, aberrations in other tumor-suppressor genes may appear even in EGFR-mutation negative cases, concealing the precedent patterns due to the initial EGFR mutations." (PMID 38102134, 2023).
tumor (continued). "Both murine SCC VII and primary human tumor cells collected from patients with HNSCC responded similarly in vitro to Rho kinase inhibition, which promoted a CD44hi tCSC phenotype additionally associated with coexpression of other stem cell markers including ALDH1A1, EpCAM, and EGFR." (PMID 37655661, 2023). "Although the association between EGFR expression and USP8 mutation status in Cushing’s disease is controversial, EGFR expression has been observed in human corticotroph tumors, and EGFR expression levels positively correlate with ACTH levels and tumor recurrence status." (PMID 36672445, 2023). "For the meta-regression analysis, we selected 9 variables (year, region, phase, immunotherapy inhibitor, anti-angiogenic drug, tumor histology, study design, EGFR mutation and whether or not to combine chemotherapy)." (PMID 37614237, 2023). "Furthermore, the anti-CD24 mAb, G7 mAb, enhances the inhibitory effect of cetuximab on tumor proliferation in vivo, suggesting that CD24 might promotes the growth of tumor cells through the regulation of EGFR expression." (PMID 38313430, 2023). "Therefore, the inappropriate activation of EGFR in tumor-localized MFAP5 + fibroblasts could partly account for its malignant behavior." (PMID 37344903, 2023). "EGFR/MET may participate in the metastasis of carcinoma through circulating tumor cells." (PMID 35428350, 2022). "If it predicts the tumor to be EGFR-mutant, clinicians may need to re-biopsy tissues." (PMID 35330479, 2022). "However, data are controversial because activated EGFR signaling allows NSCLC cells to use multiple strategies to create an immunosuppressive TME, including recruitment of Tumor-Associated Macrophages and Tregs and the production of inhibitory cytokines and metabolites." (PMID 35742933, 2022). "Therefore, the analysis of these tumor types in conjunction with HNSCC may add important insights into the molecular processes underlying these tumors, particularly the EGFR-related processes." (PMID 35154483, 2022). "Therefore, we believe that this therapeutic approach, following complete or cytoreductive resection of GBM, could lead to (i) elimination of residual or surgically inaccessible EGFR+ve cancer cells and (ii) subsequent stimulation of anti-tumour immunity." (PMID 35057796, 2022). "Indeed, we found that tumour growth could be slowed by treatment with the EGFR-inhibitor sapitinib (AZD8931/EGFRi) specifically in VilCreER;Apcfl/+;KrasG12D/+;Alk5CA mice but not in VilCreER;Apcfl/+;KrasG12D/+ mice." (PMID 36477656, 2022). "Interestingly, EGFR and NF-κB cooperate in tumor cells, amplifying their oncogenic signals." (PMID 35409325, 2022). "Moreover, a tumor growth rate ≥2.2% per month, Ki-67 index ≥3% and EGFR overexpression may be independent predictors of clinical refractoriness." (PMID 35372086, 2022). "Therefore, EGFR and c-Met promote tumor progression through signal interaction." (PMID 35978812, 2022). "Furthermore, the lower lobe has been associated with an increased proportion of non-adenocarcinoma tumours and a lower frequency of EGFR mutations, both of which are unfavourable survival characteristics." (PMID 35418206, 2022). "Therefore, blocking of EGFR in tumor cell lines (A431 and U87-MG) reduces the free uptake of B-ASO." (PMID 36499115, 2022). "Therefore, we investigated whether the available anti-EGFR mAbs induced ADCP of tumor cells by macrophages." (PMID 35035479, 2022). "The discrepancy between preclinical laboratory experiments and observations made in the clinic could be explained by the fact that some KRAS wt tumours can still activate the RAS pathway due to events other than RAS oncogene mutations, such as BRAF or EGFR mutation." (PMID 36163168, 2022). "The most frequent variant in our group was EGFR L858R, detected in 5 out of 26 (19.23%) plasma samples and in 3 out of 26 (11.53%) tumor samples, followed by the group of variants detected in codon 12 of KRAS gene (4 out of 26 or 15.38%) in plasma and tumor tissue." (PMID 36551569, 2022).
tumor (continued). "Therefore, we hypothesized that EGFR-mutant NSCLC would take advantage from ICI therapy when ferroptosis was induced in tumor tissues." (PMID 35784745, 2022). "The cellular kinase inhibition assay and mice xenograft experiment confirmed that afatinib could potently inhibit p.L747P-mutant cells and significantly reduce p.L747P-mutant tumor growth (P< 0.001), together with reduced phosphorylation of EGFR and its downstream signalings." (PMID 35223527, 2022). "Exosomal EGFR levels in the plasma of xenograft mice showed the same trend as the size of xenograft tumors, thus implying that exosomal EGFR levels could be utilized to estimate tumor size." (PMID 35158999, 2022). "SHC1 may play a tumor-promoting role by regulating EGFR signaling pathway." (PMID 35706930, 2022). "Evidence from prior research had shown that anti-EGFR antibody nimotuzumab could increase HLA class I expression in tumor cell lines, and another study found similar results showing that nimotuzumab can enhance NK cell activation and DC maturation and increase EGFR-specific T cell." (PMID 35978803, 2022). "Thus, a tumor can develop multiple mechanisms of resistance at once, which are mostly subclonal; this heterogeneity of resistant alterations calls for new treatment strategies to overcome anti-EGFR resistance." (PMID 36818675, 2022). "Additionally, all three mAbs induced antibody-dependent cellular phagocytosis (ADCP) of tumor cells by macrophages at low antibody concentrations in vitro, independent of mutations in EGFR signaling pathways." (PMID 35035479, 2022). "Liquid biopsies may be used to analyze ctDNA and provide information about a patient’s eligibility for any line of treatment with anti-EGFR mAbs and subsequent rechallenge with this therapy, as the analysis of ctDNA found in the bloodstream can reveal genetic changes occurring in the tumor." (PMID 36818675, 2022). "Therefore, as is seen in our CRC patients, the anti-tumor effects of anti-EGFR therapy alone could be expected, and differences in T-cell trafficking and immunity could be directly compared to the BsAb strategy." (PMID 35177811, 2022). "Our study also demonstrated that increased expression of TDP43 controlled by lncRNA LCETRL3 could stabilize the NOTCH1 mRNA, elevate NOTCH1 expression, downregulate PTEN expression and activate AKT in NSCLC cells, which thereby accelerating tumor growth and reduce EGFR-TKIs efficiency." (PMID 35095099, 2022). "Notably, tumor sample #8-T showed a low amount of EGFR expression, but high HX103 labeling." (PMID 36376325, 2022). "EGFR is a glycoprotein receptor on the surface of the cell membrane with tyrosine kinase activity and is the expression product of proto-oncogene Cerb-1; high expression of EGFR can promote tumor angiogenesis and the proliferation, adhesion, and invasion of tumor cells." (PMID 35582197, 2022). "Besides TGF-β receptors, other FUT8 targets such as epidermal growth factor receptor and an adhesion receptor complex, α3β1 integrin, may potentiate ligand binding ability and enhance downstream signal pathways to support tumor growth and metastasis." (PMID 35303925, 2022). "Furthermore, core-crosslinked polymeric micelles conjugated with the epidermal growth factor receptor (EGFR)-targeted Nbs reduced EGFR-mediated signaling and inhibited tumor growth in vivo, particularly when loaded with doxorubicin, and outperformed the non-targeted micelles." (PMID 36499301, 2022). "A radiomics feature extracted from the pretreatment CT scan of NSCLC patients showed a strong association with the presence of sensitizing EGFR mutations (AUC = 0.67, p = 0.03); in contrast, tumor volume and maximum diameter were both not significantly predictive of EGFR mutations (p > 0.27)." (PMID 36359485, 2022).